FOXF2 (forkhead box F2)
Diseases named in the same sentence as FOXF2 in open-access papers (continued):
Sharing a sentence is not in itself a finding about the gene and the disease.
breast carcinoma (continued). "However, the role of high ectopic FOXF2 expression in breast cancer cells remains to be explored." (PMID 31222004, 2019). "To further investigate the role of the FOXF2-CTSK axis in the interaction of breast cancer cells with bone, we performed bone-matrix invasion assays to test whether FOXF2-regulated CTSK secretion by cancer cells led to the degradation and invasion of the bone matrix." (PMID 31222004, 2019). "In many cancer types, the expression of Foxf2 is repressed by promoter hypermethylation or by oncogenic microRNAs (miRNAs), such as miR-301, which promotes breast cancer cell proliferation, invasion, and tumor growth, indicating that Foxf2 may act as a tumor suppressor." (PMID 30285803, 2018). "In addition to BLBC, we also tested the effect of FOXF2 on luminal breast cancer cells." (PMID 25848863, 2015). "Another EMT pathway, Wnt/β-Catenin, is also the common mechanism for FOXC1, FOXF2, and FOXM1 to regulate breast cancer EMT." (PMID 40003882, 2025). "FOXC1 and FOXF2 have interactions with TGF-β/Smad, which indicates their role in breast cancer cell EMT." (PMID 40003882, 2025). "For instance, FOXF2 and FOXO3 both function as tumor suppressors in HER2-positive breast cancer and have limited expression levels." (PMID 40003882, 2025). "Another transcriptional repressor of FOXQ1 is the related protein FOXF2, and in fact, FOXQ1 and FOXF2 were found to trans-repress each other in breast cancer cells as well as during embryonic development." (PMID 39777582, 2025). "For instance, FOXF2 plays diverting roles on WNT2B and FZD1 promoters in lumenal breast cancer and BLBC." (PMID 40003882, 2025). "In lung cancer, miR-301 has been reported to target MEOX2, while in breast cancer, it targets COL2A1, PTEN, BBC3, and FOXF2." (PMID 37509289, 2023). "Another TF, forkhead box F2 (FOXF2), is over-expressed in basal-like breast cancer (BLBC) cells and suppressed EMT and malignancy of these cells." (PMID 33478130, 2021). "On the other hand, previous studies have suggested that FOXF2 and FOXQ1 play opposite roles in controlling epithelial-mesenchymal transition and visceral metastasis in basal-like breast cancer cells." (PMID 33898467, 2021). "FOXF2 suppresses EMT in breast cancer and is inversely correlated with the EMT activator FOXC2.50,51 We used qRT-PCR to confirm downregulation of FOXF2 and upregulation of FOXC2." (PMID 31942031, 2020). "In this study, we identified FOXF2 as another direct regulator of CTSK transcription and CTSK-mediated breast cancer bone metastasis." (PMID 31222004, 2019). "The increased expression of Foxf2 during an EMT was assessed in normal murine mammary gland epithelial cells (NMuMG) and in murine and human breast cancer cells." (PMID 30285803, 2018). "In conclusion, our study has shown a novel Akt-PI3K pathway inhibitory role of miR301 in breast cancer cells through regulation of PI3K, PTEN and FoxF2." (PMID 26967567, 2016). "The FOXF2 gene is often inactive or “silenced” in luminal-type and HER2-positive breast cancers." (PMID 40003882, 2025). "However, abnormal FOXF2 expression occurs in a variety of human diseases, such as Axenfeld-Rieger syndrome, stroke, osteoporosis, IUA, lung cancer, gastric cancer, and breast cancer." (PMID 33717680, 2021). "FOXF2/VEGF-C/VEGFR3 and FOXF2/BMP/SMAD axes are potential therapies that could inhibit the metastasis of breast cancer cells to blood vessels and bone." (PMID 33717680, 2021). "In addition to reducing RSU1, miR-182-5p promotes tumor cell proliferation, invasion and migration by targeting FOXF2, RECK and MTSS1, and the suppression of MTSS1 (MIM) by miR-182 activates RhoA and promotes breast cancer metastasis." (PMID 32751711, 2020). "The role and mechanism of FOXF2 in regulating the non-bone distant metastasis of luminal breast cancer cells remain to be further investigated." (PMID 31222004, 2019).
breast carcinoma (continued). "Because CTSK is coexpressed with FOXF2 and the CTSK proximal promoter region contains three putative FOXF2-binding sequences, we speculated that FOXF2 may enable breast cancer cells to induce osteoclast maturation by increasing CTSK." (PMID 31222004, 2019). "Although FOXF2 was coexpressed with a set of BRGs in breast cancer, FOXF2 directly regulated some BRGs, but not others." (PMID 31222004, 2019). "The dual function of Foxf2 during EMT is underscored by the finding that high Foxf2 expression correlates with good prognosis in patients with early noninvasive stages of breast cancer, but with poor prognosis in advanced breast cancer." (PMID 30285803, 2018). "In addition, Foxf2 transcript levels are increased in more aggressive ER–, in triple negative, and in the EMT-like, claudin-low breast cancer subtypes." (PMID 30285803, 2018). "Similarly, Foxf2 is essential for the proper downregulation of E-cadherin and the regulation of Zeb2 and Id2 during a TGFβ-induced EMT of Py2T murine breast cancer cells that have been derived from a tumor of the MMTV-PyMT mouse model of breast cancer." (PMID 30285803, 2018). "However, forced ectopic expression of FOXF2 did not affect these capabilities of luminal breast cancer MCF-7 cells in the BEAS-2B cell-mimic lung microenvironment." (PMID 31222004, 2019). "However, we failed to observe any metastasis in the MCF-7-FOXF2/nude mouse ventricle injection model, and clinical data revealed that FOXF2 negatively correlated with non-bone metastasis in breast cancer cases." (PMID 31222004, 2019). "We also analyzed the relationship between FOXF2 expression and distant metastasis-free survival (DMFS) or non-bone/other organ metastasis-free survival (NBMFS) in overall cases and in different subtype cases based on our RT-qPCR data of primary breast cancer tissues." (PMID 31222004, 2019). "However, the validation data set in GOBO showed that FOXF2 mRNA level was not a prognostic factor for basal-like breast cancer population (data not shown)." (PMID 23620774, 2013). "For example, binding motifs for E2F and Fox family members, including FOXO1 (FOXO1A), FOXA1 (HNF3A), and FOXF2 (FREAC2,4), are highly enriched in PR-binding sites in breast cancer cells but not in leiomyoma cells." (PMID 22272226, 2012). "Mir-301b targets FOXF2, PTEN, and COL2A1, regulating the proliferation, colony formation, cell migration, invasion, chemotherapy resistance, and tumor growth of ductal invasive breast cancer cells without lymph node metastasis." (PMID 34796198, 2021).
lung carcinoma (14 papers, 2016 to 2023). "Our current results show FOXF2 levels were decreased in lung cancer tissue and its down-regulation is associated with the increased tumor size." (PMID 27487137, 2016). "Foxf2 expression tightly relates to the transcription factor Zeb1 and increases in mesenchymal-like metastatic lung cancer cells." (PMID 37986065, 2023). "FOXF2 is negatively regulated in six sets of lung cancer data and in the PAH set, and positively regulated in a leukemia dataset." (PMID 36101460, 2022). "In lung cancer, miRNAs of this cluster, together with the miR-200 family, inhibit forkhead box F2 (FOXF2), an inhibitor of E-cadherin." (PMID 35884446, 2022). "FOXF2, as a transcriptional regulator, was also found to have a transcriptional repression effect on the miR-200b ∼ 200a ∼ 429 locus in lung cancer." (PMID 34568422, 2021). "In lung cancer (except for non-small cell lung cancer) and rhabdomyosarcoma in mice, FOXF2 mainly shows a promotive effect." (PMID 32503970, 2020). "The strong invasion, migration and metastasis induced by FOXF2 in lung cancer cells are closely related to Zeb122." (PMID 32503970, 2020). "In this regard, it is interesting to note that miR-96 also targets Foxf2 and Ezrin mRNAs, to block the invasion and metastasis of lung cancers and renal cancers." (PMID 30509302, 2018). "In our present study, the mRNA level of FOXF2 was found to be decreased in primary lung cancer compared with paired normal lung tissue, and it negatively correlated with the size of lung cancer." (PMID 27487137, 2016). "Here we showed that DbA induced the up-regulation of CAR10 and EGFR and its downstream signaling molecules through the induction of the FoxF2-YB-1 signal cascade, contributing to lung cancer cell proliferation in vitro and in vivo." (PMID 27322209, 2016). "Significant difference in FOXF2 mRNA levels was found between paired primary lung cancers and normal lung tissues (P = 0.012, Z = −2.521)." (PMID 27487137, 2016). "To establish the link between FOXF2 mRNA levels in primary tumors and clinicopathological features of lung cancer, we analyzed the FOXF2 mRNA levels among different clinicopathologic groups." (PMID 27487137, 2016). "In these validation samples, the median mRNA level of FOXF2 in primary lung cancers was lower than that in normal lung tissues (median level, -1.450945 vs 0.16391; P = 2.40E-5)." (PMID 27487137, 2016). "The mRNA level of FOXF2 ranged from 1.79E-04 to 157.47 in primary lung cancers and the median was 5.86E-03." (PMID 27487137, 2016). "The prognostic value of expression of FOXF2 mRNA was validated in an independent dataset consisting of 17 normal lung tissues and 98 lung cancer tissues from the study of Bhattacharjee." (PMID 27487137, 2016). "First, we measured the FOXF2 mRNA levels in primary lung cancer and paired normal samples from patients with NSCLC using real-time PCR analysis." (PMID 27487137, 2016). "In addition, miR-200 family inhibits lung cancer cell invasion and metastasis by targeting Foxf2, a transcription factor that elevated in mesenchymal-like lung cancer cells." (PMID 33898432, 2021). "Many kinds of microRNAs can inhibit lung cancer by targeting FOXF2." (PMID 32503970, 2020). "MiR-182-5p and miR-183-5p were found to be up-regulated in NSCLC tissue compared with adjacent normal lung tissue, and the miR-183∼96∼182 cluster could inhibit the invasion and metastasis of lung cancer through directly suppressing the expression of Foxf2." (PMID 28445945, 2017). "Thus, further investigations are required to identify the role of FOXF2 in lung cancer and other cancer types." (PMID 27487137, 2016). "However, recent studies showed Foxf2 induced robust EMT, migration, invasion and metastasis in lung cancer cells, and inhibition of miR301 enhances Akt-mediated cell proliferation and FoxF2 is a regulatory target for miR301." (PMID 27487137, 2016). "However, the effect of smoke on FOXF2 in lung cancer needs to be investigated furtherly." (PMID 27487137, 2016).
lung carcinoma (continued). "Foxf2 expression stimulated strong EMT, migration, invasion, and metastasis in lung cancer cells, whereas Foxf2 suppression remarkably inhibited these phenotypes." (PMID 37986065, 2023). "However, the role of FOXF2 in lung cancer is unknown, especially in NSCLC." (PMID 27487137, 2016). "The miR-200 family and the miR-183~96~182 cluster which are co-repressed in lung cancer inhibit EMT and metastasis by inducing forkhead box F2 (Foxf2), which correlates with ZEB1, represses E-cadherin and forms a double-negative feedback loop with the miR-200 family." (PMID 27992370, 2017).
Stroke (14 papers, 2016 to 2026). Sudden impairment of blood flow to a part of the brain due to occlusion or rupture of an artery to the brain. "For instance, expression of 2 transcription factors in the Fb-V cluster (foxf2a, tbx18) are associated with pericytes in previous studies, although have poorly described roles, and regulatory changes in FOXF2 are associated with stroke in humans." (PMID 38683849, 2024). "In line with this, humans with risk loci near FOXF2 are more susceptible to stroke and cerebral small vessel disease." (PMID 38683849, 2024). "These SNPs were found to regulate the enhancer activity and expression of the vascular stability regulator FOXF2, thus playing a role in regulating stroke risk in both human cells and zebrafish." (PMID 39739914, 2024). "A meta-analysis of GWAS with subsequent functional validation identified common variants near FOXF2 associated with increased stroke susceptibility." (PMID 36294301, 2022). "Seven of the eight known loci associated with risk for IS were replicated in this study, and a novel locus at 6p25 (rs12204590, near FOXF2) was identified to be associated with risk for all stroke (OR:1.08, 95%CI: 1.05–1.12, p = 1·48 × 10−8)." (PMID 36294301, 2022). "Recently, a novel locus at chromosome 6p25 (rs12204590, near FOXF2) has been observed to be associated with an increased risk of stroke in European populations." (PMID 29163794, 2017). "Recently, a novel locus at chromosome 6p25 (rs12204590, near FOXF2) associated with an increased risk of stroke in European populations was identified." (PMID 29163794, 2017). "The same variants near FOXF2 were also found to be associated with larger white matter hyperintensity burden in older stroke-free community persons." (PMID 27796860, 2016). "In humans, reduced FOXF2 is associated with an increased stroke risk and SVD prevalence in humans." (PMID 41789880, 2026). "Variants associated with all type of strokes were found near FOXF2 (6p25) and ALDH2 (12q24) genes." (PMID 35052389, 2021). "In addition to FOXF2, other loci have also recently been reported to be associated with all ischemic stroke or all stroke at a genome-wide significant level." (PMID 27796860, 2016). "The deletion of EC-specific Foxf2 in adult mice resulted in blood-brain barrier leakage, which worsened after experimental stroke." (PMID 41398477, 2025). "The CHARGE (Cohorts for Heart and Aging Research in Genomic Epidemiology) Consortium reported on a locus on chromosome 6p25 near the FOXF2 gene that reached genome-wide significance for all stroke subtypes and white matter hyperintensity (WMH) burden." (PMID 35052389, 2021). "Furthermore, genetic loci (specific regions of human DNA) such as 9p21, PITX2, ZFHX3, FOXF2, and GUCY1A3 have been implicated in stroke susceptibility and subtype differentiation." (PMID 41018177, 2025). "Genetic studies have identified FOXF2 as a major risk gene for both SVD and stroke." (PMID 41398477, 2025). "First, FOXF2 SNPs have been found to affect not only stroke, but also cancer." (PMID 33717680, 2021). "Collectively, our results highlight the critical role of Foxf2-regulated Tie2 signaling in SVD and stroke, suggesting new avenues for therapeutic interventions." (PMID 41398477, 2025). "Furthermore, genome-wide association studies (GWAS) have identified loci such as 9p21, PITX2, ZFHX3, FOXF2, and GUCY1A3 as significant contributors to stroke risk and subtype differentiation, underscoring the interplay of genetic, metabolic, and demographic factors in stroke etiology." (PMID 41018177, 2025). "These loci provide insights into lacunar stroke pathogenesis, highlighting disruption of the vascular extracellular matrix (COL4A2, LOX, SH3PXD2A, GPR126, HTRA1), pericyte differentiation (FOXF2, GPR126), TGF-β signalling (HTRA1), and myelination (ULK4, GPR126) in disease risk." (PMID 33773637, 2021).
Stroke (continued). "As a key member of the forkhead box transcription factors, forkhead box F2 (FOXF2) serves as a transcriptional regulator and regulates downstream gene expression in embryonic development, metabolism and in some common diseases, such as stroke and gastroparesis." (PMID 32503970, 2020).
prostate carcinoma (12 papers, 2013 to 2025). A carcinoma that arises from epithelial cells of the prostate gland. "Several studies have reported the association between FOXF2 and prostate cancer, while our study first revealed that FOXF2 can also be a significant marker for BPH." (PMID 37705744, 2023). "We laser-captured cells in the stromal regions of prostate cancer specimens of different Gleason patterns and determined the expression of FOXF2 and genes associated with immune cells and chemokines." (PMID 36369237, 2022). "Here the authors show that reduction of Foxf2 expression in stromal cells is associated with high grade prostate cancer and that increasing prostatic stromal Foxf2 sensitizes prostate cancer to immune checkpoint blockade." (PMID 36369237, 2022). "It is tempting to speculate that loss of basal cells downregulates the expression of Foxf2, which induces tumor permissive immune microenvironment and assist in prostate cancer progression." (PMID 36369237, 2022). "In prostate cancer, the expression of forkhead box F2 (FOXF2) in the stroma correlates with CXCL5 levels, and reduced CXCL5 enhances FOXF2 expression, leading to increased T cell infiltration." (PMID 40038745, 2025). "Inhibition of miR-182-5p by an inhibitor of this microRNA also resulted in the suppression of invasion and migration in prostate cancer cells via upregulation of FOXF2, RECK, and MTSS1." (PMID 37438760, 2023). "In connection with the role of FOXF2 in suppressing the invasive activity of prostate cancer cells, it was found that this tumor suppressor inhibits the activity of Wnt5a protein and Wnt signaling pathway." (PMID 37438760, 2023). "Increasing prostatic stromal Foxf2 sensitizes prostate cancer to the immune checkpoint blockade therapies." (PMID 36369237, 2022). "We also determined the expression of FOXF2 in laser-captured stromal and tumor cells from human prostate cancer specimens of different Gleason patterns by qRT-PCR." (PMID 36369237, 2022). "The stromal FOXF2 expression level in primary prostate cancers inversely correlates with the Gleason grade." (PMID 36369237, 2022). "Here we show that increasing prostatic stromal Foxf2 suppresses the growth and progression of both syngeneic and autochthonous mouse prostate cancer models in an immunocompetent context." (PMID 36369237, 2022). "For example, we showed that the expression of CXCL6 and CXCL8, the functional homologs of mouse Cxcl5, are both inversely correlated with that of FOXF2 in human prostate cancer specimens." (PMID 36369237, 2022). "Augmenting lung stromal Foxf2 also mediates an immunosuppressive milieu and inhibits lung colonization of prostate cancer." (PMID 36369237, 2022). "To extend this finding in human prostate cancer, we took an unbiased bioinformatic approach to investigate the correlation between FOXF2 expression and cytotoxic T cells." (PMID 36369237, 2022). "We also showed that increasing Foxf2 expression in lung stroma can suppress prostate cancer colonization." (PMID 36369237, 2022). "Collectively, these observations imply that stromal FOXF2 plays a potential role in prostate cancer progression." (PMID 36369237, 2022). "Bioinformatic analysis shows that the expression level of FOXF2 inversely correlated with the Gleason scores of the primary prostate cancer specimens in two independent human prostate cancer datasets." (PMID 36369237, 2022). "In this study, we take a combination of bioinformatic, molecular, cellular, and genetic approaches and reveal a mechanism in which stromal Foxf2 suppresses prostate cancer progression and metastasis by enhancing antitumor immunity." (PMID 36369237, 2022). "In-vitro studies showed that the knock-down of miR-182-5p in prostate cancer cell can promote cell proliferation, migration and invasion by regulating the potential targets of FOXF2, RECK and MTSS1." (PMID 32102688, 2020).